VSTM2L (V-set and transmembrane domain containing 2 like)
Synonyms: C20orf102; dJ1118M15.2
Tractability: Antibody: its Gene Ontology location is reachable by antibodies, with high confidence; UniProt predicts a signal peptide or a membrane-spanning region. PROTAC: its protein half-life has been measured.
Gene: Protein-coding gene on chromosome 20 (37,903,111 to 37,945,350, forward strand). Ensembl gene ENSG00000132821.
Gene Ontology:
Molecular function: protein binding
Biological process: negative regulation of neuron apoptotic process
Cellular component: cytoplasm; extracellular region; membrane
Genetic constraint (gnomAD): Loss-of-function variants: 9 observed, 18.44 expected, observed/expected ratio (o/e) 0.49, 90% interval 0.29 to 0.85. The upper end of that interval is the gene's LOEUF score, 0.85, which puts it in group 3 of 6, group 1 being the genes least tolerant of losing a copy. Missense variants: 286 observed, 261.88 expected, observed/expected ratio (o/e) 1.09, 90% interval 0.99 to 1.2. Synonymous variants: 127 observed, 118.1 expected, observed/expected ratio (o/e) 1.08, 90% interval 0.93 to 1.25.
Homologues: Orthologues: macaque VSTM2L (100% identical), chimpanzee VSTM2L (99% identical), guinea pig VSTM2L (99% identical), pig VSTM2L (98% identical), rabbit VSTM2L (97% identical), mouse Vstm2l (94% identical), dog VSTM2L (56% identical), tropical clawed frog vstm2l (53% identical), zebrafish vstm2l (49% identical), Drosophila melanogaster Bsg (14% identical), Caenorhabditis elegans zig-11 (10% identical). Paralogues in human: BSG (20% identical), NPTN (20% identical), EMB (15% identical).
Diseases named in the same sentence as VSTM2L in open-access papers:
VSTM2L is named in the same sentence as 16 diseases in open-access papers, as found by Europe PMC text mining. Sharing a sentence is not in itself a finding about the gene and the disease. The quoted sentences say what the papers report.
gastric cancer (2 papers, 2021). A primary or metastatic malignant neoplasm involving the stomach. "Moreover, the VSTM2L gene was considered a novel CIMP-related prognostic marker to classify gastric cancer patients into high- and low-risk groups with significant difference in overall survival time." (PMID 33506057, 2021). "A negative correlation was found between VSTM2L and CIMP, and a CIMP-related gene signature comprising six genes (VSTM2L, CST6, SLC7A2, RAB3B, IGFBP1, and EVX2) stratified gastric cancer patients into high‐ and low-risk groups with distinct prognoses." (PMID 35155565, 2021). "It was previously reported that VSTM2L was expressed at a low level and predicted poor prognosis in gastric cancer and rectal cancer, which was confirmed by our observations in STAD." (PMID 35155565, 2021). "Consistent with the mRNA levels, VSTM2L showed lower expression in both gastric cancer and colon cancer tissues than in normal tissues." (PMID 35155565, 2021). "In recent years, there are a few studies that described the expression and clinical relevance of VSTM2L in cancer; the mRNA level of VSTM2L is lower in gastric cancer tissues than in adjacent normal tissues and was downregulated in the H. pylori-positive gastric cancer." (PMID 33506057, 2021). "VSTM2L was shown to be downregulated in Helicobacter pylori-positive gastric cancer compared to corresponding normal tissues; additionally, the CpG island methylation phenotype (CIMP)-related gene signature comprising VSTM2L and five other genes showed prognostic value in gastric cancer." (PMID 35155565, 2021). "Although a few studies have been reported about its gene expression and clinical relevance in gastric cancer, there is still lack of researches on the functional role and potential molecular mechanism of VSTM2L in cancer." (PMID 33506057, 2021). "A previous study has shown that VSTM2L was downregulated in H. pylori-positive gastric cancer patients compared to patients who were H. pylori-negative in TCGA and was expressed at a lower level in gastric cancer tissue compared to adjacent normal tissue, which was supported by our work." (PMID 35155565, 2021).
Cognitive impairment (1 paper, 2025). Abnormal cognition is characterized by deficits in thinking, reasoning, or remembering. "The coordinated downregulation of mitochondrial genes (Lars2, Vstm2l) alongside KEAP1-NFE2L2 pathway suppression suggests potential molecular pathways whereby IH exposure may affect cellular antioxidant defenses and mitochondrial function, possibly contributing to cognitive impairment." (PMID 40806623, 2025).
colorectal cancer (1 paper, 2021). A primary or metastatic malignant neoplasm that affects the colon or rectum. "The overexpression of VSTM2L in colorectal cancer cells induced resistance to CRT via promoting cell proliferation and inhibiting apoptosis." (PMID 33506057, 2021). "And then, we constructed VSTM2L-overexpressing colorectal cancer cells in vitro to investigate the functional role of VSTM2L high expression." (PMID 33506057, 2021). "Taken together, these results indicated that overexpression of VSTM2L induced resistance to CRT in colorectal cancer cells through promoting cell proliferation and DNA damage repair and inhibiting cell apoptosis when cancer cells were treated with CRT." (PMID 33506057, 2021).
Ewing sarcoma (1 paper, 2021). A small round cell tumor that lacks morphologic, immunohistochemical, and electron microscopic evidence of neuroectodermal differentiation. "RNA-seq data in the CCLE database showed that VSTM2L was highly expressed in Ewing sarcoma cell line." (PMID 35155565, 2021).
migraine (1 paper, 2022). "To conclude, our study suggests that CCDC141 and VSTM2L are associated with increased risks of RLS in patients with migraine." (PMID 35350973, 2022). "By using a two-stage GWAS, we identified two novel susceptibility genes, VSTM2L and CCDC141, accountable for an increased risk of RLS in patients with migraine." (PMID 35350973, 2022). "Our data confirmed the crucial role of VSTM2L and CCDC141 in RLS in patients with migraine; however, pre-existing information regarding these two genes is scarce." (PMID 35350973, 2022). "We have used translational knockdowns (morphants), transcriptional knockdowns, and transient knockouts (crispants) in the zebrafish system to examine the functional relationship of CCDC141 and VSTM2L to the symptoms of RLS and migraine and obtained relatively consistent results." (PMID 35350973, 2022).
neuroblastoma (1 paper, 2025). Neuroblastoma (NB) is the most common solid, extracranial childhood tumor. "Meanwhile, three independent neuroblastoma cohorts (Kocak, SEQC, TARGET) consistently revealed significantly elevated expression of NRCAM, VSTM2L, SLIT3, and ALCAM in Stage 4S tumors." (PMID 40448172, 2025).
prostate carcinoma (1 paper, 2025). A carcinoma that arises from epithelial cells of the prostate gland. "Simultaneously, VDAC1 binding protein V-Set and transmembrane domain containing 2-like protein (VSTM2L) are positively correlated with prostate cancer (PCa) progression and are key regulators of ferroptosis." (PMID 40959280, 2025).
rectal cancer (1 paper, 2021). A primary or metastatic malignant neoplasm that affects the rectum. "A higher mortality rate was observed in high-risk CIMP patients with elevated expression of prognostic genes including VSTM2L; and in rectal cancer patients receiving preoperative chemoradiotherapy, high VSTM2L expression was correlated with poor therapeutic response and adverse clinical outcomes." (PMID 35155565, 2021).
restless legs syndrome (1 paper, 2022). A condition that occurs while resting or lying in bed; it is characterized by an irresistible urgency to move the legs to obtain relief from a strange and uncomfortable sensation in the legs. "We identified two novel susceptibility loci rs6021854 (in VSTM2L) and rs79823654 (in CCDC141) to be associated with restless legs syndrome in migraineurs, which remained significant when compared to normal controls." (PMID 35350973, 2022). "Our GWAS and functional analysis suggest VSTM2L and CCDC141 are highly relevant to the pathogenesis of restless legs syndrome in migraineurs." (PMID 35350973, 2022).
cancer (4 papers, 2021 to 2025). A tumor composed of atypical neoplastic, often pleomorphic cells that invade other tissues. "In this study, we found that VSTM2L expression differed between tumor and normal tissues and that this was linked to the clinical outcomes in various cancer types." (PMID 35155565, 2021). "Taken together, the significant expression of tumor-infiltrating immune cells, immunostimulators, immunoinhibitors, major histocompatibility complex molecules, among others in various cancers point to an association between changes in VSTM2L and disease prognosis and development." (PMID 35155565, 2021). "Both are present at nerve endings; V‐set and transmembrane domain‐containing two like (VSTM2L, also known as C20orf102), is a secreted protein that modulates the activity of humanin in neural cells and is involved in neurodegenerative diseases and cancer." (PMID 39910963, 2025). "Our results also demonstrate for the first time that aberrant expression of VSTM2L was associated with the TIME including TIICs, immunostimulators, immunoinhibitors, MHC molecules, TMB, MSI, and immune and stromal scores in various cancers." (PMID 35155565, 2021). "We found that VSTM2L was related to TIICs in most cancers with the exception of DLBC, GBM, and THYM." (PMID 35155565, 2021). "In conclusion, VSTM2L has prognostic value in various cancers and can predict both poor (STAD) and good (KIRP) outcomes." (PMID 35155565, 2021). "Our results demonstrated that VSTM2L was significantly upregulated in 11 cancers and downregulated in 11 cancers." (PMID 35155565, 2021). "Overexpression of VSTM2L in cancer cells treated with CRT was analyzed for the function of cell proliferation and viability, clone formation, DNA damage repair, and apoptosis ability." (PMID 33506057, 2021). "V-set and transmembrane domain containing 2 like (VSTM2L) regulates interleukin (IL)-4 signaling pathway—which involves immune-related factors—and has been linked to some cancers." (PMID 35155565, 2021). "VSTM2L is a novel molecule described as an uncharacterized function gene in cancer." (PMID 33506057, 2021). "The overexpression of VSTM2L induced resistance to CRT in cancer cells." (PMID 33506057, 2021). "We analyzed VSTM2L expression in different cancers; the TIMER data across all TCGA tumors showed that compared to corresponding normal tissue, VSTM2L was significantly upregulated in BRCA, KIRP, LUAD, PAAD, PCPG, PRAD, and THCA and downregulated in COAD, GBM, KICH, KIRC, LUSC, STAD, and UCEC." (PMID 35155565, 2021). "Therefore, the dysregulation of VSTM2L and immune markers among cancer patients suggest a crucial role of VSTM2L in the modulation of TIME." (PMID 35155565, 2021). "Further study is needed to clarify the reasons for the dual role of VSTM2L in cancers." (PMID 35155565, 2021). "Thus, we have identified that overexpression of VSTM2L induced resistance to CRT in cancer cells through downstream IL-4 signaling which could affect the progress of cell proliferation and apoptosis." (PMID 33506057, 2021). "Thus, the regulation of VSTM2L modulates cancer development and progression." (PMID 35155565, 2021). "However, there have been few studies on the role of VSTM2L in cancer." (PMID 35155565, 2021). "In summary, we showed that VSTM2L has distinct expression patterns, prognostic value, and relationship with the TIME of different cancers." (PMID 35155565, 2021). "To explore the underlying downstream molecular mechanisms that VSTM2L overexpression induces resistance to CRT in cancer cells, we performed gene set enrichment analysis (GSEA) on the microarray data from GSE45404, GSE68204, GSE87211, and VSTM2L-overexpressing RNA sequence." (PMID 33506057, 2021). "High VSTM2L expression was associated with shorter OS in BLCA, KIRC, OV, STAD, THYM, UCEC, and UVM but predicted better outcome in KIRP; VSTM2L expression had no prognostic value in the OS of other cancers." (PMID 35155565, 2021).
cancer (continued). "It is worth noting that VSTM2L had prognostic value in high TMB STAD patients and low TMB KIRP patients; the opposite effects may imply that VSTM2L has distinct immunomodulatory functions in these cancers." (PMID 35155565, 2021). "However, the expression profile and prognostic significance of VSTM2L in different cancers as well as its relationship to the TIME are not known." (PMID 35155565, 2021). "We, therefore, investigated the relationship between aberrant VSTM2L expression and TIICs, immunomodulators, TMB, MSI, and immune and stromal scores in different cancers, which has not been previously reported." (PMID 35155565, 2021).
tumor (3 papers, 2021 to 2023). "We found that VSTM2L high expression is positively associated with poor tumor response and survival prognosis in rectal cancer patients receiving pCRT." (PMID 33506057, 2021). "High expression of VSTM2L was significantly associated with tumor regression after pCRT (P = 0.030)." (PMID 33506057, 2021). "Advanced tumor stage was more closely associated with VSTM2L expression in BLCA, COAD, KIRC, STAD, and THCA, while the opposite was true for KIRP." (PMID 35155565, 2021). "Furthermore, the rectal cancer patient-derived tumor organoids were used to identify the association of VSTM2L expression and tumor response to CRT." (PMID 33506057, 2021). "In addition, we cultured rectal cancer patient-derived tumor organoid to identify the association of VSTM2L expression and tumor response when those tumor organoids were treated with CRT in vitro." (PMID 33506057, 2021). "High VSTM2L expression was also related to advanced tumor status (T2 vs T3, p = .0018; T2 vs. T4, p = .00053) and node status (N0 vs N2, p = .0074; N0 vs. N3, p = .017) in STAD patients irrespective of sex and age." (PMID 35155565, 2021). "In our study, we used GEO dataset analysis and considered VSTM2L high expression as a biomarker for prediction of poor tumor response and survival prognosis of rectal cancer patients receiving pCRT." (PMID 33506057, 2021). "To further explore the association of VSTM2L expression and tumor response to CRT, we preoperatively collected fresh tumor tissues from rectal cancer patients receiving pCRT to culture for patient-derived organoid in vitro." (PMID 33506057, 2021). "In contrast, in KIRP, high VSTM2L expression was related to early tumor stage, better differentiation, and lower rate of metastasis." (PMID 35155565, 2021). "Based on transcription data from The Cancer Genome Atlas (TCGA), we identified four tumour-specific antigens for vaccine production: ARPC1B, ELF3, VSTM2L, and IL27RA." (PMID 37779866, 2023). "Thus, ARPC1B, ELF3, VSTM2L, and IL27RA were identified as potential tumour antigens for mRNA vaccine production." (PMID 37779866, 2023). "The mRNA levels of VSTM2L were significantly downregulated in normal rectal tissues compared to tumor tissues and were upregulated in nonresponders of rectal cancer patients receiving pCRT and positively correlated with poor survival prognosis from GEO datasets." (PMID 33506057, 2021). "VSTM2L was significantly downregulated in tumor compared to normal tissues in GSE87211 and upregulated significantly in tumor tissues of nonresponders to pCRT in the GSE45404 and GSE68204 datasets." (PMID 33506057, 2021).
infection (1 paper, 2024). The state of being infected such as from the introduction of a foreign agent such as serum, vaccine, antigenic substance or organism. "Only one gene, Vstm2l, was significantly downregulated at 4 dpi and upregulated later during infection at 12 dpi." (PMID 38536871, 2024).
metabolic disease (1 paper, 2024). A congenital disorder (due to inherited enzyme abnormality) or acquired (due to failure of a metabolically important organ) disorder resulting from an abnormal metabolic process. "VSTM2L is involved in neuroprotection as well as in neurogenerative and metabolic diseases." (PMID 38674069, 2024).
VSTM2L also shares sentences with these, for which no sentence is quoted: colon cancer (1 paper); memory impairment (1); neurodegenerative disease (1).